WT1 (WT1 transcription factor)
Diseases named in the same sentence as WT1 in open-access papers (continued):
Sharing a sentence is not in itself a finding about the gene and the disease.
tumor (continued). "In this study, the tumor expressed WT1 focally, and NUT protein was diffusely and uniformly deeply stained, consistent with the reported literature." (PMID 40255429, 2025). "Originally identified as a tumor suppressor in Wilms’ tumors, WT1 has also been recognized for its oncogenic role in various solid tumors and blood-related cancers." (PMID 40507300, 2025). "This translocation results in an active fusion protein involving the Ewing sarcoma (EWS) and Wilms tumor (WT1) genes and is pathognomonic for the diagnosis.9) DSRCT can metastasize early and recur rapidly despite treatment." (PMID 40034204, 2025). "Of note, the repression of WT1 and FOXA1, elicited by the signature, caused a downregulation of the Androgen Receptor (AR) expression, an impairment of tumor-spheroid formation and reversed cancer cell stemness." (PMID 40399259, 2025). "Instructive examples were two children in whom we sampled bilateral tumours, as well as multiple biopsies from the one side (PD50643, germline WT1 predisposition; PD52239, early mosaic chromosome 11p LOH shared between blood and kidney)." (PMID 39665570, 2025). "Wilm’s tumor (Wt1), which is involved in radiation sensitization, apoptosis, and DNA repair mechanism, has been suggested to increase the radiation sensitivity upon its downregulation." (PMID 41282050, 2025). "In our patient, the histology analysis revealed a favorable histology made of a triphasic tumor, and immunohistochemistry showed positivity for WT1 and PAX8." (PMID 39844890, 2025). "When unbound, miR-23a can bind and induce the translational repression of WT1, a critical tumour suppressor in ovarian cells." (PMID 39736850, 2025). "The sponging of miR-23a by lncRNA GAS5 relieves WT1 from translational suppression, allowing it to exert its tumour inhibiting function to halt tumour progression." (PMID 39736850, 2025). "WT1 is a tumor-suppressor gene located on chromosome 11 that plays a critical role in genitourinary system development." (PMID 41373846, 2025). "The results revealed that tumor cells exhibited significantly elevated expression levels of WT1, SIX1, SIX2, and CITED1, supporting the accurate annotation of tumor cells." (PMID 40534868, 2025). "Being expressed in several tumors, WT1 has been included among the main tumor antigens considered in developing cancer vaccines." (PMID 40399259, 2025). "The most common method for creating ex vivo DC vaccines for NSCLC is to separate patient autologous monocytes, turn them into DCs, and then load them with tumor-associated antigens (TAAs), like mucin 1 (MUC1), Wilms’ tumor 1 (WT1), or customized neoantigens." (PMID 41002418, 2025). "Transcriptomic analyses revealed the same pattern: WT1-mutant tumours with aberrant Wnt signalling clustered separately." (PMID 39665570, 2025). "While we observed down regulation of Calretinin in all primary cells compared to the tumor tissues, the remaining markers for mesothelial cell origin, including Podoplanin and WT1, remained positive." (PMID 39920655, 2025). "A specific interest goes to Wilms’ tumor protein 1 (WT1) which has an acknowledged role as a tumor oncogene in a variety of malignancies, including AML." (PMID 39259326, 2025). "This vaccination inhibited WT1-expressing tumor development in mice by enhancing the cytotoxic activity of WT1 epitope-specific cytotoxic T cells." (PMID 39594765, 2024). "In a patient-derived RCC xenograft tumor model, WT1-specific CTLs regenerated from induced pluripotent stem cells (iPSCs) showed therapeutic efficacy." (PMID 38929778, 2024). "We assessed WT1/TD reactivity in adult RCC tumor cells, tumor microenvironment (TME), and tumor-adjacent healthy renal tissue (HRT)." (PMID 38929778, 2024).
tumor (continued). "The tumor microenvironment's immunosuppressive nature adds to the complexity and represents another significant challenge for WT1 vaccines." (PMID 38665761, 2024). "We identified a relationship between BAP1 driver mutations and the epigenetic upregulation of EMT genes (IL20RB and WT1), correlating with increased tumour immune infiltration, advanced stage, and poorer patient survival." (PMID 39592856, 2024). "A powerful immune system response was induced by the upregulation of WT1 and TAAs mediated by the ICD of tumor cells, which caused further DCs maturation." (PMID 38742454, 2024). "Areas with high WT1 expression showed sparse T-cell infiltrates, consistent with an immune evasive tumor microenvironment." (PMID 38190392, 2024). "The cell was discovered to have traits resembling those of the original tumor tissue and to express calretinin, WT-1, and cytokeratin 5/6." (PMID 38200517, 2024). "These in vivo observations are consistent with a model whereby vFLIP induces WT1, which in turn recruits MDSCs to the tumor microenvironment." (PMID 38190392, 2024). "Histopathological distinction of ENOC tumors from HGSOC is challenging, but the use of some discriminatory immunohistochemistry tools such as Wilms’ tumor 1 (WT1) lead to better tumor classification." (PMID 39876896, 2024). "The existence of long-term viable WT1-specific CD8+ T cells is important for the long-term anti-tumor effect." (PMID 39509060, 2024). "Immunohistochemistry showed the positive expression of CD31, CD34, α-SMA, GLUT1 and WT-1 in the tumor tissue, and the tumor was eventually diagnosed as an infantile haemangioma." (PMID 38267947, 2024). "Regarding intratumoral positivity, out of the 30 cases investigated, only 2 RCCs showed WT1 immunoexpression, whereas the broad majority, 23 RCCs, demonstrated TD reactive tumor tissues." (PMID 38929778, 2024). "The DAMPs and upregulation of WT1 facilitated DC activation, and mature DCs presented these antigens to T cells to trigger a robust tumor‐specific T cell response." (PMID 38742454, 2024). "Nowadays, the WT1 protein has been identified as a tumor antigen and is one of the top target molecules for immunotherapy in cancer." (PMID 39768169, 2024). "In conclusion, these results suggest that the WT1 protein in tumor cells is highly immunogenic, thereby stimulating endogenous naïve-type WT1126-CTLs and enabling them to clonally expand and differentiate into effector-type WT1126-CTLs." (PMID 39509060, 2024). "mRNA vaccines show optimal properties for the activation of CTL responses, the PSB@Nb1.33C/mRNA induced WT1‐specific T cells immune responses were investigated to explore the enrichment of WT1‐specific CTLs within the tumor." (PMID 38742454, 2024). "Herein, for all 30 RCCs, the tumor-adjacent HRT consistently showed WT1 nuclear reactivity, specifically in podocytes and epithelial cells, i.e., within the parietal layer of Bowman’s capsule." (PMID 38929778, 2024). "Histologic sections were subjected to triple indirect sequential IF using WT1 to detect MM tumor cells, CD11c to identify M1 macrophages, and CD163 to identify M2 macrophages." (PMID 38592450, 2024). "The Wilms' tumor 1 (WT1)‐pulsed DC vaccination therapy derived stable disease in 50% of the patients treated with WT1‐pulsed DC vaccination, with neurological improvements and tumor shrinkage observed in 20% of these patients." (PMID 39215399, 2024). "In fact, one study found that knockout of WT1 in mouse endothelial, hematopoietic and myeloid derived suppressor cells (MDSCs), led to decreased tumor growth and metastases, and that WT1 was critical to recruiting MDSCs to suppress T cell immune responses." (PMID 38190392, 2024).
tumor (continued). "The nanosystem killed 4T1 tumor cells via PTT under NIR laser irradiation in vitro and delivered the WT1 mRNA encoding tumor‐associated antigens to APCs within the tumor in vivo." (PMID 38742454, 2024). "Monotherapies with either WT1-TCB or Ven/Aza inhibited tumor growth (day 36: 1850 ± 432 mm3 and 1316 ± 213 mm3, respectively), compared to the corresponding vehicle control (2528 ± 468 mm3)." (PMID 38212534, 2024). "Conversely, although both WT1-positive RCCs were also reactive to TDs, the higher-grade tumor showed a more significant TD expression pattern (QS = 3, IS = 2 vs. QS = 2, IS = 1)." (PMID 38929778, 2024). "The excellent photothermal therapeutic (PTT) properties of PSB and 2D iMxene (Nb1.33C) trigger tumor immunogenic cell death, which boosts the release of the WT1 mRNA." (PMID 38742454, 2024). "There are various peptide-based cancer vaccines that target tumor-associated antigens like NY-ESO-1, MAGE-A, and WT1." (PMID 38893147, 2024). "TAAs are derived from normal proteins that are overexpressed in tumor cells, such as Wilms’ tumor 1 (WT1) or prostate-specific antigen (PSA)." (PMID 39594730, 2024). "Recent RNA-sequencing data compared primary and recurrent DSRCT samples as well as cell lines suggesting the EWSR1::WT1 fusion protein as a principal driver with enrichment in genes regulated by the fusion protein in the recurrent versus primary tumor." (PMID 39411551, 2024). "The aim of this study is to investigate the predictive and prognostic role of BAP1, WT1 and calretinin expression and their combinations in pre-treatment tumor samples by immunohistochemical (IHC) staining." (PMID 38280040, 2024). "WT1 positivity was scarce and strictly nuclear in tumor cells, whereas TD-reactive tumor tissues were prevalent." (PMID 38929778, 2024). "In turn, WT1 expression, in conjunction with expression of other viral genes, leads to an immunosuppressive and angiogenic tumor microenvironment." (PMID 38190392, 2024). "Wilms' tumor 1 (WT1)‐pulsed DC vaccination therapy resulted in stable disease in 50% of patients, with neurological enhancements and tumor regression observed in 20% of these cases." (PMID 39215399, 2024). "Remarkably, the tumor size decreased significantly to 12 mm, a 65.7% reduction, after combined therapy with eight doses of WT1/MUC1-DC and erlotinib for 237 days." (PMID 38336778, 2024). "The aim of this study is to investigate the role of BAP1, WT1, calretinin expression and their combinations in tumor tissue samples by IHC staining in predicting response and prognosis in PM patients treated with chemotherapy alone." (PMID 38280040, 2024). "BAP1 analyses were performed on formalin-fixed, paraffin-embedded tumor tissue samples of the patients, while WT1 and calretinin information were obtained from the histopathological diagnosis records." (PMID 38280040, 2024). "In 2007, the first report of WT1 peptide vaccination in advanced RCC showed suppressed tumor growth and stable disease in two out of three patients." (PMID 38929778, 2024). "WT1 has been shown to have oncogenic activities in cancer, including growth promotion, differentiation inhibition, resistance to cell death, and tumor angiogenesis facilitation, despite its original characterization." (PMID 38665761, 2024). "The light‐driven and hypoxia‐driven properties are used to deliver Wilms' tumor 1 (WT1) mRNA to the tumor region." (PMID 38742454, 2024). "WT1 plays a pivotal role in maintaining the transformation of cancers and tumor escape from immune surveillance." (PMID 39737308, 2024). "WT1 is a bidirectional transcription factor with dual functions of inhibiting tumor growth and activating oncogene transcription." (PMID 38702814, 2024). "In this system, named PSB@Nb1.33C/mRNA, photosynthetic bacteria (PSB) efficiently delivers the iMXene‐WT1 mRNA to the core tumor region using photo‐driven and hypoxia‐driven properties." (PMID 38742454, 2024).
tumor (continued). "The expression of DAMPs and upregulation of the WT1 protein considerably facilitated DC activation, and the mature DCs presented these antigens to T cells to induce a strong tumor‐specific T cell response." (PMID 38742454, 2024). "Key mutations in genes like WT1, CTNNB1, and WNT, for example, have been linked to the onset and progression of the tumor, as well as its response to treatment, thus providing new avenues for targeted therapy." (PMID 39062028, 2024). "The binding partner to the WT1 protein, Wilms’ tumor 1-associating protein (WTAP), has been suggested to have an oncogenic role in many tumor types." (PMID 38173713, 2023). "A total of 29325 CD45+ immune cell profiles were obtained from six tumor samples (WT1, n = 5197; WT2, n = 5358; WT3, n = 3917; KO1, n = 5131; KO2, n = 6432; and KO3, n = 3290)." (PMID 36650153, 2023). "The number of tumor-infiltrating WT1-specific CD8+ lymphocytes was demonstrated to be two-fold higher in mice treated with DSP-7888 Emulsion plus anti-PD-1 vs DSP-7888 Emulsion plus an isotype control antibody (1.76 vs 0.80%)." (PMID 36138335, 2023). "Wilms’ tumour gene 1 (WT1) is clearly recognized as a tumour promoter in diversiform of human malignancies." (PMID 37667197, 2023). "Immunohistochemically, the tumor cells are immunoreactive for cytokeratins and desmin and show strong nuclear expression for WT1 (C terminus) and harbor a distinctive EWSR1-WT1 fusion in the molecular pathology." (PMID 37518334, 2023). "Taken together, these data suggest that WT1 TED2 split can elicit potent cytotoxicity against tumor cells at physiological pMHC target density." (PMID 38022650, 2023). "In this study, it is unclear through what mechanism the induction of cytotoxic T cells targeting the WT1 antigen elicited by WT1-DC affects the anti-tumor immunity of the body as a whole." (PMID 38143707, 2023). "Additional tumor-associated antigens have been tested including survivin (phase II study of SurVaxM vaccine in newly diagnosed GBM: NCT02455557) and WT1 (multiple clinical trials underway using DSP-7888 for pediatric HGGs and progressive GBM)." (PMID 36874119, 2023). "WT1 was reported to manifest both tumor suppressive and oncogenic activities in different cancer types due to its interaction with various proteins leading to transcriptional activation or repression of different genes." (PMID 37580757, 2023). "Pediatric tumor-related studies demonstrated that the Wt1 gene had been shown to play an important role in renal progenitor differentiation and tumor suppression." (PMID 36829196, 2023). "While the WT1 peptide, derived from functional protein domains, has shown substantial potential as a cytotoxic agent against tumor cells in Prof. Travassos’ pioneering work, its antimicrobial properties remain unexplored." (PMID 37725261, 2023). "WT1 protein expression in tumor cells was confirmed in most patients recruited for this clinical trial." (PMID 36672344, 2023). "WT1 has been described as an oncogene and its high expression has been detected in several different types of neoplasms, such as breast cancer, mesothelioma, and leukemias." (PMID 36960966, 2023). "In conclusion, our findings in this preclinical model of oncolytic viral therapy demonstrate the capacity of RV Wt1-5 for tumor spread." (PMID 37186587, 2023). "WT1-CAR-T cells were used against WT1+/HLA-A*02:01 + primary tumor cells or cell lines with satisfactory results." (PMID 37803464, 2023). "The Wilms’s tumor gene Wt1, which activates Fst (follistatin) during follicle development, was also downregulated in F1–D1 ovaries." (PMID 36982971, 2023). "In fact, in hypoxic conditions, HIF can activate WT1 in vascular cells to promote angiogenesis at the tumor site." (PMID 38173713, 2023).
tumor (continued). "Collectively, our data highlights that tumor-specific epigenetic remodeling is tightly related to MECOM, PAX8, SOX17 and WT1 activity and these transcription factors are targetable in a tumor-specific manner through transcriptional inhibitors." (PMID 37090516, 2023). "WT1 and CTNNB1 variants often co-occur in WT and the spatial distribution of CTNNB1 variants has been demonstrated to exhibit intra-tumor genetic heterogeneity." (PMID 38110397, 2023). "In this study, the WIP2W peptide halted the cell cycle in the G0/G1 phase and reduced WT1 protein levels in tumor tissues." (PMID 37765274, 2023). "In contrast to the WT1 TED that showed reduced cytotoxicity, WT1 TED2 split demonstrated significantly augmented cytotoxicity against two WT1-HLA-A*02:01+ tumor cell lines." (PMID 38022650, 2023). "In order to further explore the relationship between WT1 and tumour immune microenvironment (TME), we calculated the immune infiltration abundance of patients in TCGA-LUAD cohort through CIBERSORT algorithm." (PMID 37667197, 2023). "In a subsequent clinical trial, we will continue administering the WT1 Trio peptide vaccine to patients in whom the WT1 Trio is considered to slow tumor growth." (PMID 36672344, 2023). "Despite its tumor-suppressive activities, elevated WT1 expression has been discovered in tumors derived from epithelial, mesenchymal, hematopoietic, and neuronal tissues, suggesting its paradoxical oncogenic function." (PMID 38173713, 2023). "WT1 levels were found to be higher in cancer cells relative to adjacent, non-tumor tissue, while CDH1 levels were lower in the cancer cells as compared to the cancer-adjacent tissue." (PMID 36864480, 2023). "WT1-specific adoptive immunotherapy has been the “hot spot” for tumour treatment, which exhibit promising antineoplastic effect with tolerable safety." (PMID 37667197, 2023). "Researchers have discovered that peptides produced from intracellular WT1 can be expressed in the context of human leukocyte antigen on the surface of tumor cells (HLA)." (PMID 37330575, 2023). "As a tumor suppressor gene, Wt1 has long been used in the model of the Wt1-Cre system and is a reliable marker of the origin and fate of embryonic ECs." (PMID 36923960, 2023). "After two weeks of treatment, the silencing of the WT1 protein resulted in an important antitumor activity that reduced the tumor weight." (PMID 36960966, 2023). "Scholars recognize WT1 as a widespread tumour antigen, and recently, it ranks top in a list of 75 candidate cancer antigens." (PMID 37667197, 2023). "Twenty-five patients consented for WT1 testing of their tumor (MSK protocol #15-247; NCT02737787) between June 2016 and July 2017." (PMID 36900251, 2023). "WT1 represents an ideal target for tumor-directed immunotherapy in EOC, as it is an oncofetal antigen with expression in normal adult tissues limited to kidney, ovary, testis, spleen, and mesothelial lining but with overexpression in EOC cells." (PMID 36900251, 2023). "To further explore the utility of WT1 TED2 split to target WT1-HLA-A*02:01+ tumors, we obtained WT1-HLA-A*02:01+ primary AML cells, given that primary AML cells have more physiological expression of WT1-HLA-A*02:01 than tumor cell lines." (PMID 38022650, 2023). "Several studies have used the wild-type or modified major histocompatibility complex (MHC) class I restricted WT1 peptides for generation of vaccination against WT1 overexpressing tumor cells and leukemic blasts." (PMID 37444601, 2023). "This reduction in tumor volume was accompanied by increased numbers of tumor-infiltrating WT1-specific CTLs." (PMID 36138335, 2023).